ZNF777 (zinc finger protein 777)
Description:
May be involved in transcriptional repression. Inhibits cell proliferation through CDKN1A/p21 induction by down-regulation of NIBAN1/FAM129A at low cell density.
Synonyms: KIAA1285
Tractability: PROTAC: UniProt records ubiquitination sites on it; ubiquitination databases record sites on it.
Gene: Protein-coding gene on chromosome 7 (149,431,363 to 149,461,062, reverse strand). Ensembl gene ENSG00000196453.
Subcellular location: Nucleus
Subcellular location (Human Protein Atlas): Nucleoplasm
Pathways (Reactome):
Gene expression (Transcription): Generic Transcription Pathway
Gene Ontology:
Molecular function: protein binding; DNA-binding transcription factor activity; DNA-binding transcription factor activity, RNA polymerase II-specific; RNA polymerase II cis-regulatory region sequence-specific DNA binding
Biological process: negative regulation of cell population proliferation; negative regulation of DNA-templated transcription; protein heterooligomerization; regulation of transcription by RNA polymerase II; regulation of DNA-templated transcription
Cellular component: nucleus
Genetic constraint (gnomAD): Loss-of-function variants: 7 observed, 66.02 expected, observed/expected ratio (o/e) 0.11, 90% interval 0.059 to 0.2. The upper end of that interval is the gene's LOEUF score, 0.2, which puts it in group 1 of 6, group 1 being the genes least tolerant of losing a copy. Missense variants: 828 observed, 1,097.3 expected, observed/expected ratio (o/e) 0.75, 90% interval 0.71 to 0.8. Synonymous variants: 545 observed, 484.11 expected, observed/expected ratio (o/e) 1.13, 90% interval 1.05 to 1.21.
Homologues: Orthologues: chimpanzee ZNF777 (99% identical), macaque ZNF777 (99% identical), rabbit ZNF777 (94% identical), dog ZNF777 (94% identical), pig ZNF777 (93% identical), mouse Zfp777 (92% identical), rat Zfp777 (92% identical), guinea pig ZNF777 (91% identical). Paralogues in human: ZNF398 (34% identical), ZNF746 (30% identical), ZNF287 (20% identical), ZKSCAN7 (20% identical), ZNF530 (18% identical), ZNF527 (18% identical), ZNF776 (18% identical), ZNF774 (18% identical), ZNF852 (18% identical), ZNF17 (17% identical), ZNF416 (17% identical), ZNF34 (17% identical), and 38 more.
Diseases named in the same sentence as ZNF777 in open-access papers:
ZNF777 is named in the same sentence as 10 diseases in open-access papers, as found by Europe PMC text mining. Sharing a sentence is not in itself a finding about the gene and the disease. The quoted sentences say what the papers report.
Parkinson disease (1 paper, 2019). A progressive degenerative disorder of the central nervous system characterized by loss of dopamine producing neurons in the substantia nigra and the presence of Lewy bodies in the substantia nigra and locus coeruleus. "ZNF746 attracted our interest because of its involvement in Parkinson’s disease and ZNF777 because of its old evolutionary age." (PMID 31856708, 2019).
ZNF777 also shares sentences with these, for which no sentence is quoted: bladder cancer (1 paper); cancer (1); cervical cancer (1); cutaneous melanoma (1); hepatocellular carcinoma (1); leiomyosarcoma (1); lung carcinoma (1); prostate carcinoma (1); renal carcinoma (1).